CYP4V2 (cytochrome P450 family 4 subfamily V member 2)
Description:
A cytochrome P450 monooxygenase involved in fatty acid metabolism in the eye. Catalyzes the omega-hydroxylation of polyunsaturated fatty acids (PUFAs) docosahexaenoate (DHA) and its precursor eicosapentaenoate (EPA), and may contribute to the homeostasis of these retinal PUFAs. Omega hydroxylates saturated fatty acids such as laurate, myristate and palmitate, the catalytic efficiency decreasing in the following order: myristate > laurate > palmitate (C14>C12>C16). Mechanistically, uses molecular oxygen inserting one oxygen atom into a substrate, and reducing the second into a water molecule, with two electrons provided by NADPH via cytochrome P450 reductase (CPR; NADPH-ferrihemoprotein reductase).
Synonyms: CYP4AH1; BCD
Tractability: Small molecule: it belongs to a druggable protein family. Antibody: UniProt predicts a signal peptide or a membrane-spanning region. PROTAC: ubiquitination databases record sites on it; its protein half-life has been measured.
Gene: Protein-coding gene on chromosome 4 (186,191,475 to 186,215,245, forward strand). Ensembl gene ENSG00000145476.
Subcellular location: Endoplasmic reticulum membrane
Subcellular location (Human Protein Atlas): Nuclear speckles
Pathways (Reactome):
Metabolism: Endogenous sterols
Sensory Perception: The canonical retinoid cycle in rods (twilight vision)
Gene Ontology:
Molecular function: protein binding; oxidoreductase activity, acting on paired donors, with incorporation or reduction of molecular oxygen, NAD(P)H as one donor, and incorporation of one atom of oxygen; heme binding; iron ion binding; long-chain fatty acid omega-hydroxylase activity; medium-chain fatty acid omega-hydroxylase activity; monooxygenase activity; oxidoreductase activity, acting on paired donors, with incorporation or reduction of molecular oxygen
Biological process: fatty acid omega-oxidation; retinoid metabolic process; sterol metabolic process; fatty acid metabolic process
Cellular component: endoplasmic reticulum membrane
Genetic constraint (gnomAD): Loss-of-function variants: 54 observed, 60.16 expected, observed/expected ratio (o/e) 0.9, 90% interval 0.72 to 1.13. The upper end of that interval is the gene's LOEUF score, 1.13, which puts it in group 4 of 6, group 1 being the genes least tolerant of losing a copy. Missense variants: 672 observed, 662.62 expected, observed/expected ratio (o/e) 1.01, 90% interval 0.95 to 1.08. Synonymous variants: 239 observed, 231.43 expected, observed/expected ratio (o/e) 1.03, 90% interval 0.93 to 1.15.
Gene-disease validity (ClinGen):
ClinGen rates the evidence that CYP4V2 causes each of these diseases.
Bietti crystalline corneoretinal dystrophy (autosomal recessive): Definitive.
Homologues: Orthologues: chimpanzee CYP4V2 (99% identical), macaque CYP4V2 (88% identical), rabbit CYP4V2 (85% identical), rat Cyp4v3 (83% identical), mouse Cyp4v3 (82% identical), dog CYP4V2 (81% identical), pig CYP4V2 (78% identical), guinea pig CYP4V2 (78% identical), zebrafish cyp4v2b (61% identical), tropical clawed frog cyp4v2.2 (60% identical), zebrafish cyp4v2a (58% identical), Drosophila melanogaster Cyp4c3 (47% identical), and 27 more. Paralogues in human: CYP4F11 (33% identical), CYP4F2 (33% identical), CYP4F22 (33% identical), CYP4F8 (33% identical), CYP4F3 (33% identical), CYP4F12 (32% identical), CYP4B1 (32% identical), CYP4A11 (32% identical), CYP4A22 (31% identical), CYP4X1 (31% identical), CYP4Z1 (31% identical), CYP19A1 (20% identical).